ELN (elastin)
Diseases named in the same sentence as ELN in open-access papers (continued):
Sharing a sentence is not in itself a finding about the gene and the disease.
cutis laxa (23 papers, 2012 to 2026). Cutis laxa (CL) is an inherited or acquired connective tissue disorder characterized by wrinkled, redundant and sagging inelastic skin associated with skeletal and developmental anomalies and, in some cases, with severe systemic involvement. "The constellation of clinical, radiologic, genetic, and histopathologic findings supports a diagnosis of cutis laxa, representing a potential mild phenotype affecting both the integumentary and vascular systems associated with c.484G>A ELN variant." (PMID 41451031, 2026). "Another autosomal dominant disorder caused by mutations in the ELN is Cutis laxa typified by loose and/or wrinkled skin that imparts a prematurely aged appearance." (PMID 40650005, 2025). "Mutations in Elastin and Fibulin-5 gene have been reported to associate with patients developing cutis laxa." (PMID 35054981, 2022). "Mutations involving ELN gene are causative of cutis laxa, which has an association with aortic dilatation that was found in 30–50% of patients." (PMID 35892496, 2022). "The variability of COPD incidences among smokers is also explained by a genetic pre-disposition, such as α1-antitrypsin deficiency and cutis laxa [mutation of the elastin gene (ELN)]." (PMID 30455693, 2018). "Mutations in the FBLN5 gene result in cutis laxa and are potentially linked to age-related macular degeneration, a disease characterized by degradation of the elastin support structures." (PMID 28116311, 2017). "Indeed, in the skin of cutis laxa patients, elastic tissue varies in content, appearance, proportion, and the way in which elastin and microfibrillar components are associated." (PMID 37408270, 2023). "ELN mutations resulting in autosomal-dominant cutis laxa are known to be associated with different phenotypes of aging (cutis laxa and cardiovascular and musculoskeletal abnormalities), and the DCN mutation leads to abnormal collagen fibril morphology and skin fragility." (PMID 30574417, 2018). "The Atp6v0a2−/− and Atp6v0a2RQ/RQ mouse models both recapitulate the ARCL2A/WSS/ATP6V0A2-CDG phenotype with cutis laxa-like skin changes due to reduced elastin deposition." (PMID 39680136, 2024). "Missense substitutions leading to improper secretion of FBLN5 and reduced interaction with elastin and fibrillin-1 have been reported in recessive cutis laxa." (PMID 36794549, 2023). "Regarding the non-syndromic presentation of TAA, a triplication around the elastin gene was found to segregate in a family with supravalvular non-syndromic aortic aneurysm and in which the diagnosis of cutis laxa was excluded." (PMID 35892496, 2022). "The mechanical role of elastin is manifested in diseases such as cutis laxa, in which skin is characterized by abnormal wrinkling and laxity due to structural defects in the extracellular matrix or in the synthesis of elastin." (PMID 34138349, 2021). "Loss of elasticity as part of the healthy aging process, and disorders such as cutis laxa that occur due to defects in mature elastin, demonstrate the need for elastin in engineered skin substitutes to fully recapitulate normal healthy skin." (PMID 34198681, 2021). "The term cutaneous asthenia in humans is reserved for cases where abnormalities in both collagen and elastin (cutis laxa) exist." (PMID 31546637, 2019). "These proteins included several important ECM components, periostin (POSTN), elastin (ELN), and decorin (DCN); genetic mutations in these proteins are associated with different phenotypes of aging, such as cutis laxa and joint and dermal manifestations." (PMID 30574417, 2018). "Several gene defects, such as those in elastin or fibulin 5, have been found in cutis laxa, suggesting an etiology of defects in elastic fiber synthesis." (PMID 28116317, 2016).
cutis laxa (continued). "Some other monogenetic lung disorder-related genes were enriched in specific SAE cell types, including BC (LTBP4, ELN, cutis laxa), ionoctyes (HPS5, Hermansky-Pudlak syndrome), mucin-producing cells (COL1A1, Ehlers-Danlos syndrome), and neuroendocrine cells (BMPR2, pulmonary hypertension)." (PMID 32727470, 2020). "These manifestations were initially vesicular and blistering lesions that subsequently evolved to the destruction of elastin fibers leading to large areas of cutis laxa in both patients, a phenomenon also described in the APLAID patient with the p.Leu848Pro PLCG2 variant." (PMID 32671674, 2020). "Decreases in proline levels may affect collagen and elastin synthesis in connective tissues, leading to cutis laxa." (PMID 30574417, 2018). "However, a detailed mechanism of how Elastin and fibulin-5 are involved in the development of cutis laxa is unknown." (PMID 35054981, 2022). "Histologic analysis of skin from cutis laxa patients identified reduced elastin levels with less-well defined collagen fibers lacking the characteristic wavy morphology." (PMID 26569114, 2015).
lung disease (23 papers, 2010 to 2025). "Elastin and fibrillin gene mutations highlight the importance of elastin to lung development and suggest that loss of elastin is linked with susceptibility to destructive lung disease." (PMID 37001705, 2023). "The role of degraded skin elastin contributing to a systemic pro-inflammatory state linked to progression of lung disease is unknown, though studies evaluating the utility of a byproduct of elastin cleavage, desmosine, as a biomarker of pulmonary disease have been inconclusive to date." (PMID 31234847, 2019). "While elastin is important to tissue architecture and possesses unique mechanical properties which have been studied more extensively in cardiovascular and pulmonary disease, little work has been done related to biomechanics of elastin and carcinogenesis." (PMID 37001705, 2023). "Lung diseases are often characterized by irreversible damage to connective tissue elastin and collagen fiber networks." (PMID 37031200, 2023). "These comprehensive measurements establish a foundation for constructing much needed structurally representative collagen and elastin degenerative constitutive models to improve our understanding of pulmonary disease progression." (PMID 37031200, 2023). "Lung diseases often express high collagen deposition as a physiological response to restrengthen the tissue after elastin degradation." (PMID 37031200, 2023). "One characteristic of pulmonary disease is the inability of lung tissue to recoil due to elastin and collagen fiber remodeling." (PMID 37031200, 2023). "Elastin is a crucial protein required for alveolar maturation and lung development, and, in adults, is a marker of lung disease severity and progression." (PMID 34445540, 2021). "As the main clinical phenotype under study in the COPDGene cohort is lung disease, it appears reasonable to assume that the origin is the lungs, although elastin and collagen are both abundant in other major organs of the body such as the skin." (PMID 28103932, 2017). "This is consistent with the finding of decreased elastin in aged native lungs and also has implications for increased fibrogenesis in aging-related lung diseases." (PMID 26954258, 2016). "The aim of this study was to identify and quantify NE-generated elastin degradation, and assess the relationship between levels of elastin fragments and pulmonary disorders such as lung cancer and IPF that involve excessive lung tissue remodeling." (PMID 25935650, 2015). "In contrast, our ability to correlate elastin-specific T cell responses in smokers to declines in functional performance in the 6MWT point to the fundamental importance of autoimmunity in lung disease in smokers." (PMID 22969766, 2012). "The arteriosclerosis was characterized by intimal and medial hyperplasia, smooth muscle cell hyperplasia and fragmented and disorganized elastin fibers, and the pulmonary disease was characterized by panlobular enlargement of air spaces." (PMID 22998683, 2012). "Thus, these stimuli are frequently used for animal models of pulmonary disease related to elastin degradation and fibrosis." (PMID 37001705, 2023). "Stabilizing elastin and preventing the release of EDPs may help reduce the pathogenesis of pulmonary disease." (PMID 37001705, 2023). "Given the reduction in lung elastin for people with WS and elastin haploinsufficiency, there is an expectation that the condition could produce clinically significant pulmonary disease." (PMID 35741248, 2022). "Similarly, results from the Study of Health in Pomerania also described a restrictive type of lung disease in 73 patients with type 1 diabetes, pointing to widespread collagen and elastin abnormalities as a main etiopathogenic mechanism." (PMID 32344939, 2020). "ELM-2 was compared with ELM in both cardiovascular and pulmonary disease cohorts to investigate whether these two sub-pools of elastin fragments provide different information." (PMID 23805173, 2013).
lung disease (continued). "Nevertheless, increased elastin degradation in any tissue may affect systemic function by compromising the elasticity and function of vital organs, such as the skin, heart, and lungs, potentially contributing to cardiovascular or pulmonary diseases." (PMID 41340653, 2025). "Thus, systemic inflammation stemming from elastin degradation in pulmonary disease may perpetuate disease and promote pathogenesis in other organs." (PMID 37001705, 2023). "Consequently, to be used therapeutically, early diagnosis and treatment of elastin mediated pulmonary disease may yield more efficacious results." (PMID 35665242, 2022). "Elastin is a signature protein of the arteries and lungs, thus it was hypothesized that elastin is subject to enzymatic degradation during cardiovascular and pulmonary diseases." (PMID 23805173, 2013). "Further, larger, clinical studies are needed to confirm the diagnostic value and also to evaluate the prognostic potential in lung disease, and the potential utility of this neoepitope in other diseases in which elastin degradation may be a pivotal pathological feature." (PMID 22818364, 2012). "Thus, we hypothesized that a MMP-9/-12 generated fragment of elastin may be a relevant biochemical maker for lung diseases." (PMID 22818364, 2012). "This study suggests relationships between CVD and lung disease in AATD, with a proposed mechanism being proteinase-driven breakdown of elastin fibres in the large arteries and lungs." (PMID 38515138, 2024). "Our data indicated that in cardiovascular tissue, elastin degradation by MMP-9 and-12 leads to the release of the ELM-2 neoepitope while the degradation in pulmonary diseases leads to the release of the ELM neoepitopes." (PMID 23805173, 2013). "VEGF sequestration by the mesenchymal sFlt transgene causes a decrease in surfactant production, increased parenchymal elastin and smooth muscle, and a decrease in alveolarization that culminate in a late restrictive lung disease pattern without grossly affecting angiogenesis." (PMID 26863115, 2016). "Additionally, environmental factors such as smoking or pollution that may synergize with elastin insufficiency to accelerate pulmonary disease, were not evaluated in the current study." (PMID 35741248, 2022). "In addition, our study is not able to disentangle whether elastin degradation is a marker of vascular disease rather than of lung disease." (PMID 31357639, 2019).
myocardial infarction (22 papers, 2013 to 2025). Gross necrosis of the myocardium, as a result of interruption of the blood supply to the area, as in coronary thrombosis. "A recent study has shown that myocardial infarction caused alterations to elastin, which is another major component of the extracellular matrix that contributes to compliance." (PMID 34713972, 2021). "As post-myocardial infarction (MI) cardiac remodeling progresses, elastin is replaced by fibrous collagenous tissue, and EDPs can be detected in patient serum." (PMID 37001705, 2023). "Typically, following myocardial infarction/ischaemia, elastin levels will decrease, promoting ECM remodelling, which further increases the stiffness of the cardiac tissue and impairment of cardiac function." (PMID 37498175, 2023). "Studies show visualization of elastin after myocardial infarction using an elastin-binding contrast agent in a mouse model." (PMID 36235031, 2022). "In this study, we have demonstrated the feasibility of in vivo monitoring of elastin formation after myocardial infarction in mouse models of selective monocyte suppression using an elastin-specific MR contrast agent, ESMA." (PMID 34040032, 2021). "In vivo MRI in mouse models of MI can detect elastin deposition after myocardial infarction, highlighting the pivotal role of elastin in myocardial remodeling in mouse models with deletions of monocyte populations." (PMID 34040032, 2021). "This study demonstrates the feasibility of in vivo monitoring of elastin formation after experimental myocardial infarction in knockout mouse models of selective monocyte suppression with an elastin binding contrast-agent." (PMID 34040032, 2021). "Compared to wild type mice, MCP-1-KO mice exhibited smaller infarcted areas with low elastin content and smaller volumes at day 7 and 30 days after myocardial infarction with a good ejection fraction during both time-points." (PMID 34040032, 2021). "The elastin to collagen III ratio was significantly higher in aortic punch tissues from myocardial infarction patients." (PMID 31827539, 2019). "miRNAs from the miR-29 family have been shown to play a role in cardiac fibrosis after myocardial infarction targeting collagen, fibrillin and elastin genes." (PMID 29940860, 2018). "Finally, we demonstrated, for the first time, that Chdlr1 treatment reduces not only collagen but also elastin deposition after myocardial infarction." (PMID 40963931, 2025). "Reduced elastin expression is observed post human myocardial infarction." (PMID 36986034, 2023). "Following a tissue injury such as myocardial infarction, fibroblasts undergo activation to myofibroblasts and contribute to fibrosis via deposition of extracellular matrix components, such as collagens and elastin." (PMID 37409168, 2023). "Cardiac fibrosis, characterised by accumulation of collagen and elastin, drives adverse cardiac remodelling and heart failure after myocardial infarction (MI)." (PMID 40963931, 2025). "Studies have shown that NE has the capacity to degrade elastin, collagen and fibrinogen, thereby contributing to damage after myocardial infarction (MI)." (PMID 36033503, 2022). "(a and b from myocardial infarction tissues; c from age-matched control) SHG light discriminates collagen I with a better signal to noise ratio than PR, while autofluorescence highlights elastin and other components in the myocytes." (PMID 23409139, 2013).
keloid (18 papers, 2013 to 2026). An irregularly shaped, elevated mark on the skin caused by deposits of excessive amounts of collagen during wound healing. "The excessive ECM components, such as collagen, fibronectin, elastin, proteoglycans, as well as matrix-directed protease and protease inhibitors, in keloids are caused by the accumulation of KFs." (PMID 33817252, 2020). "Collagen and elastin fibers, as important components of the ECM, are closely associated with keloid scar progression." (PMID 37038546, 2023). "It has been reported that the keloid matrix lacks elastin fibers, hyaluronic acid, and dermatopontin, leading to stiffness in keloid tissues." (PMID 37587491, 2023). "They reported after injection with the steroid, the cultured keloid spheres regressed and expression of collagen I, collagen III, elastin and fibronectin was reduced just like in keloid tissue in the skin." (PMID 35529910, 2022). "Recently, we were also able to reconstruct keloids in vitro with keloid-derived keratinocytes and fibroblasts, using a collagen-elastin scaffold." (PMID 32528951, 2020). "Correspondingly, there was a considerable decrease in the expression of typical ECM components, including type I and III collagen, fibronectin, and elastin, in glycyrrhizin-treated keloid spheroids (*** p < 0.001)." (PMID 31450620, 2019). "Taken together, these data strongly suggest that expressions of the major ECM components such as collagen type I and III, elastin, and fibronectin are significantly decreased by knockdown of mortalin expression in primary keloid spheroid." (PMID 29021584, 2017). "The expression levels of type-I and -III collagen, fibronectin, and elastin were also significantly reduced in keloid tissue explants after treatment with dE1-k35/sLRP6E1E2." (PMID 29118355, 2017). "Some studies reported in the literature refer to the distribution of elastin and fibrillin in mature and hypertrophic scars and keloids." (PMID 23840249, 2013). "High level of MMP-9 is found to degrade collagen, elastin, and other components of the extracellular matrix and promotes the migration and proliferation of fibroblasts, which leads to the continuous expansion of keloid tissue." (PMID 39654616, 2024). "Therefore, a fully automated approach that provides a comprehensive understanding of the keloid scar by gathering information from both collagen and elastin fibers and accurately identifies the scar boundary region is highly needed." (PMID 37038546, 2023). "Other ECM constituents also expressed at higher levels in keloid fibroblasts include fibronectin, elastin, glycosaminoglycans, and both small and large proteoglycans." (PMID 32528951, 2020). "This may explain several observations in keloids, for example, the decreased elastic fiber density in keloids despite normal elastin expression coding for elastic fibers." (PMID 31440236, 2019). "Additionally, the expression levels of type-I and -III collagen, fibronectin, and elastin in keloid tissue explants transduced with the sLRP6E1E2-expressing Ad were investigated by immunohistochemistry." (PMID 29118355, 2017). "The most important histological manifestation of keloids is the overgrowth of atypical fibroblasts with excessive amassing of extra-cellular matrix components, particularly collagen, proteoglycans fibronectin and elastin." (PMID 26391582, 2015). "In addition, the expression levels of type-I and -III collagen, elastin, and fibronectin in keloid tissue explants transduced with dEl-k35/sLRP6E1E2 was reduced by 50%, 55%, 58%, and 51%, respectively, in comparison to dE1-k35/LacZ-treated keloid tissue explants." (PMID 29118355, 2017). "While hypertrophic scars consist of αSMA positive cells and parallel rows of collagen I, keloids mostly consist of αSMA negative cells, abundant elastin, and non-organized collagen I and III." (PMID 40076946, 2025).
keloid (continued). "Keloids, considered benign fibroproliferative tumors, represent a form of pathological scarring of the skin characterized by an excessive accumulation of extracellular matrix (ECM) components such as collagen, fibronectin, and elastin." (PMID 38892032, 2024). "They observed a decrease in elastin expression, which has a positive effect on the regeneration of keratinized gingiva without leaving hypertrophic scars or keloids." (PMID 33557038, 2021). "In agreement with our interactome, regulation of ELN, COL5A2, FSTL1 and COL1A1 was demonstrated experimentally using a miR-29b mimic and antagomir in primary human skin fibroblasts and other models in the context of treatment of keloid formation and fibroplasia using miR-29b mimic Remlarsen." (PMID 39883689, 2025).